CDC25C (cell division cycle 25C)
Diseases named in the same sentence as CDC25C in open-access papers (continued):
Sharing a sentence is not in itself a finding about the gene and the disease.
glioblastoma (7 papers, 2017 to 2025). The most malignant astrocytic tumor (WHO grade IV). "Its aberrant expression in glioblastoma significantly influences tumor cell survival and radioresistance, potentially through interference with the cell cycle via CaMKII, cdc25C, and cdc2 following channel activation." (PMID 40535121, 2025). "Specifically, hispolon can induce cell cycle G2/M arrest in glioblastoma cells by suppressing the expressions of cyclin B1, cell division cycle 2 (CDC2), and M-phase inducer phosphatase 3 (CDC25C), which are three major regulatory proteins of cell cycle." (PMID 36678599, 2023). "Since p-(Tyr15)-cdc2 is a substrate of the phosphatase cdc25C, these data suggest a TRPM8-triggered signaling to cdc2 involving CaMKII and cdc25C in irradiated glioblastoma cells." (PMID 29221175, 2017).
lung adenocarcinoma (7 papers, 2017 to 2026). A carcinoma that arises from the lung and is characterized by the presence of malignant glandular epithelial cells. "Here, it was revealed that cell division cycle 25C (CDC25C) expression was upregulated in lung adenocarcinoma (LUAD) compared to that of normal lung tissue in multiple databases." (PMID 35574406, 2022). "Finally, a comprehensive analysis of TCGA, GEPIA and Kaplan-Meier Plotter databases revealed that high mRNA expression of CCNB1, CDC25C, CENPM, and EXO1 was associated with poor survival in lung adenocarcinoma patients." (PMID 35646074, 2022). "CDC25C is able to interact with 14-3-3τ and ζ in lung adenocarcinoma A549cells." (PMID 29111562, 2017). "The mRNA levels of cell division cycle 25C (CDC25C), a phosphatase that regulates G2/M cell cycle transition in malignant cells, correlate with poor clinical outcomes in lung adenocarcinoma (LUAD)." (PMID 36830899, 2023).
glioma (6 papers, 2016 to 2025). A benign or malignant brain and spinal cord tumor that arises from glial cells (astrocytes, oligodendrocytes, ependymal cells). "Moreover, it was noticed that mahanine caused cell cycle arrest in glioma cancerous cells by the downregulation of M-phase inducer phosphatase 3 (Cdc25c), cell division cycle protein 2 homolog (Cdc2), and cyclin B1." (PMID 35009050, 2021). "We demonstrated that cdc25C is a possible intermediate of the effect of TMZ/TRAM-34 on glioma cell death." (PMID 27096953, 2016). "Recently, Cdc20 was reported to be a key factor in maintaining tumorigenic glioma tumor initiating cells through degradation of p21 and regulation of Cdc25C (cell division cycle 25C), c-Myc, and Survivin." (PMID 27626499, 2016). "Finally, PI staining flow cytometry, qPCR and WB showed that NaB blocked the cell cycle of glioma cells by downregulating CDC2, CDC25C, CCNA2 and CCNB cell cycle-related proteins." (PMID 40297576, 2025).
melanoma (6 papers, 2011 to 2025). A malignant, usually aggressive tumor composed of atypical, neoplastic melanocytes. "The treatment of melanoma cells with compound 7 also caused a reduction of the CDC25C protein levels, although with a late kinetics." (PMID 26474275, 2015). "Compound 7 arrested melanoma cells in G2/M, causing a reduction of the protein levels of CDC25A and, more consistently, of CDC25C." (PMID 26474275, 2015). "Thus, one important regulator of CDK1/cyclin B1 complex, CDC25C, is suggested to be a potential oncotarget for melanoma." (PMID 30745871, 2019). "Further analysis showed that CDC25A, not CDC25B or CDC25C, plays a more dominant role in melanoma development." (PMID 40216745, 2025). "Taken together, our studies demonstrate that, within the CDC25 family, CDC25A, rather than CDC25B or CDC25C, plays a more dominant role in melanoma progression." (PMID 40216745, 2025).
pancreatic cancer (5 papers, 2009 to 2025). "Other markers, such as AQP5, CDC25C, and TMEM170B, have been proved to be associated with the prognosis of pancreatic cancer." (PMID 35898870, 2022). "For example, it has been reported that inhibition of PPP2R1A radiosensitizes pancreatic cancer via activation of CDC25C/CDK1, thus, PPP2R1A is a target gene for local therapy of pancreatic cancer." (PMID 29697368, 2018). "To conclude, our present observations state that curcumin treatment potentially inhibits the proliferation of BxPC-3 human pancreatic cancer cells by DNA damage-mediated G2/M cell cycle arrest by the activation of ATM/Chk1/Cdc25C and inhibition of cyclin B1/Cdk1 expression." (PMID 19401701, 2009).
vulvar carcinoma (5 papers, 2010 to 2020). "High expression of CDC25C was also observed in 63% of vulvar cancers, and these results further support changes in the expression of CDC25C in relation to tumorigenesis." (PMID 32518522, 2020). "We suggest from our present data that in vulvar carcinomas, 14-3-3γ and ε are the two most likely isoforms to form complexes with phospho-CDC25C (Ser216) and to thereby regulate CDC25C function." (PMID 21935479, 2011). "Expression of CDC25A, CDC25B, CDC25C and phosphorylated (phospho)-CDC25C (Ser216) were examined in 300 vulvar carcinomas using immunohistochemistry." (PMID 20500813, 2010). "High nuclear CDC25A and CDC25B expression were observed in 51% and 16% of the vulvar carcinomas, respectively, whereas high cytoplasmic CDC25C expression was seen in 63% of the cases." (PMID 20500813, 2010). "Interestingly, our previous analysis of the same cohort of vulvar carcinoma cases revealed that 70% of the tumors displayed a high nuclear expression of phospho-CDC25C (Ser216)." (PMID 21935479, 2011). "Compared to the low level of cytoplasmic phospho-CDC25C (Ser 216) protein expression in basal layers of normal vulvar squamous epithelium, high phospho-CDC25C (Ser 216) protein expression was found in the cytoplasm of 50% and in the nucleus of 70% of vulvar carcinomas." (PMID 20500813, 2010). "In the present study, overexpression of CDC25A, CDC25B and CDC25C isoforms was not significant associated with each other, suggesting that overexpression of multiple isoforms in vulvar carcinomas occur through independent pathways." (PMID 20500813, 2010). "Interestingly, a different immunostaining pattern was seen between the two CDC25C antibodies in vulvar carcinomas." (PMID 20500813, 2010). "However, in the present study high expression of CDC25C was observed in 63% of vulvar carcinomas, a finding in line with studies on prostate, colorectal and endometrium carcinomas." (PMID 20500813, 2010). "Therefore, we speculated that in vulvar carcinomas the epitope in the phospho-CDC25C (Ser 216) domain supposed to be recognized by anti-CDC25C (phosphorylated and dephosphorylated) may be masked for some unknown reasons resulting in lost nuclear staining." (PMID 20500813, 2010). "Therefore, high nuclear expressions of phospho-CDC25C (Ser 216) in the majority of cases indicate that phospho-CDC25C (Ser 216) may be important in the carcinogenesis of vulvar carcinomas and would be a potential target for cancer therapy." (PMID 20500813, 2010). "There was a clear downregulation of cell cycle regulators CDC25C, CDK1, and Cyclin A in both lines and cleavage of caspase 3, suggesting that CHK1 inhibition affects both proliferation and apoptosis of vulvar cancer cells." (PMID 29963769, 2018). "Our results suggest that CDC25C and phospho-CDC25C (Ser216) play a crucial role and CDC25B a minor role in the pathogenesis and/or progression of vulvar carcinomas." (PMID 20500813, 2010). "Our results suggest that CDC25C and phospho-CDC25C (Ser216) play a crucial role and CDC25B a minor role in the development and/or progression of vulvar carcinomas." (PMID 20500813, 2010). "However, high phospho-CDC25C (Ser 216) expression was correlated with low expression of CDC25A and high expression of CDC25B, suggesting that the three can collaborate in the tumorigenesis of a subset of vulvar carcinomas." (PMID 20500813, 2010). "Furthermore, no coexpression of CDC25B and phospho-CDC25C (Ser216) was seen in serial sections of vulvar carcinomas." (PMID 20500813, 2010).
acute myeloid leukemia (4 papers, 2014 to 2023). Acute myeloid leukemia (AML) is a group of neoplasms arising from precursor cells committed to the myeloid cell-line differentiation. "Approximately 44% of patients with familial platelet disorders that are predisposed to hematologic malignancies caused by autosomal dominant RUNX1 mutations progressed to acute myeloid leukemia caused by second-hit mutations in CDC25C or other genes." (PMID 36515795, 2023). "Studies have shown that in lung, gastric, bladder, prostate, esophageal squamous cell carcinoma, breast, acute myeloid leukemia, and colon cancers CDC25C is more highly expressed than in normal tissues." (PMID 32518522, 2020).
leukemia (4 papers, 2013 to 2025). A malignant (clonal) hematologic disorder, involving hematopoietic stem cells and characterized by the presence of primitive or atypical myeloid or lymphoid cells in the bone marrow and the blood. "Its overexpression is associated with poor prognosis in leukemia patients and inhibition of CDC25C can lead to cell cycle arrest and apoptosis." (PMID 41424711, 2025). "CDC25C, is targeted by miR-16-5p, which influences its expression and potential role in leukemia progression." (PMID 41424711, 2025). "A novel mikanolide derivative has been found to exhibit potent antileukemic activity by inhibiting CDC25C phosphorylation, triggering apoptosis, and promoting DNA damage in leukemia cells." (PMID 41424711, 2025). "In human leukemia cells, inhibitors of ERK have been reported to increase the phosphorylation of cdc25c expression at the G2/M arrest stages and decrease p21 and CDK2 expression at the endoreduplication stages." (PMID 24137330, 2013). "Moreover, in contrast to leukemia cells, treatment did not induce protein phosphorylation changes in Chk1 (Ser345), Cdc25c (Ser216), and Cdc2 (Tyr 15) neither increased levels of phospho-H2A.X." (PMID 26542114, 2015).
lymphoma (4 papers, 2015 to 2025). A malignant (clonal) proliferation of B- lymphocytes or T- lymphocytes which involves the lymph nodes, bone marrow and/or extranodal sites. "It has been reported that CDC25C is associated with cell cycle arrest in macrophages 77 and T-cell leukemia/lymphoma cells." (PMID 39247594, 2024). "Similarly, PRC1 and CDC25C mRNA levels in various AML cell lines were significantly higher compared to lymphoma cell lines." (PMID 40034437, 2025).
endometrial cancer (3 papers, 2013 to 2018). Primary or metastatic malignant neoplasm involving the endometrium (mucous membrane that lines the endometrial cavity). "Eupatilin, a naturally occurring flavonoid isolated from Artemisia princeps, has been reported to inhibit the growth of human endometrial cancer cells via activating the Chk2/Cdc25C/Cdc2 pathway." (PMID 29734760, 2018). "Jaceosidin inactivates Cdc25C-Cdk1 through ATM-Chk1/Chk2 activation, resulting in cell cycle G2/M arrest in endometrial cancer cells." (PMID 26147394, 2015).
HIV-1 infection (3 papers, 2008 to 2025). The type species of lentivirus and the etiologic agent of acquired immunodeficiency syndrome (AIDS). "Our results showed that rs3756766-A in Cdc25C was significantly associated with increased susceptibility to HIV-1 infection." (PMID 37468905, 2023). "To determine if 14-3-3 interactions were altered by Vpr or HIV-1 infection, we examined the association of 14-3-3 θ with Cdk1, CyclinB1, and Cdc25C by co-immunoprecipitation (IP)." (PMID 18445273, 2008). "However, no study reported the association between the polymorphisms of Cdc25C and HIV-1 infection and AIDS progression." (PMID 37468905, 2023). "However, we were unable to detect any redistribution of phospho-Cdc25C caused by Vprv or HIV-1 infection." (PMID 18445273, 2008). "Rs34660854 and rs37568165 in ATR gene, rs12576279 and rs540436 in Chk1 gene, rs3756766 in Cdc25C and rs139245206 in CDK1 gene were associated with susceptibility to HIV-1 infection." (PMID 37468905, 2023). "In this study, 42 tSNPs in ATR, Chk1, Cdc25C and CDK1 gene were genotyped to analyze the association with susceptibility to HIV-1 infection and AIDS progress among MSM population in the northern China." (PMID 37468905, 2023). "In this study, we aimed to genotype SNPs of ATR, Chk1, Cdc25C and CDK1 genes at G2/M checkpoint and analyze their associations with the susceptibility to HIV-1 infection and AIDS progression in a northern Chinese MSM population." (PMID 37468905, 2023). "Therefore, GMDR software was used to investigate the impact of interaction between ATR, Chk1, Cdc25C and CDK1 gene polymorphisms on HIV-1 infection susceptibility." (PMID 37468905, 2023). "Although nuclear levels did not change, Vprv, but not HIV-1 infection, significantly increased cytoplasmic expression specifically of CyclinB1 and Polo-like kinase 1 (Plk1), but not Cdc25C and Cdk1." (PMID 18445273, 2008).
liver cancer (3 papers, 2020 to 2026). An epithelial or non-epithelial malignant neoplasm that arises from the liver. "Costunolide upregulates Chk2 (Thr68), p-Cdc25c (Ser216), p-Cdk1 (Tyr15), and cyclin B1 in liver cancer (HA22T/VGH) cells." (PMID 35651747, 2022).
vulvar squamous cell carcinoma (3 papers, 2010 to 2022). An invasive squamous cell carcinoma arising from the vulva. "In vulvar squamous cell carcinomas, overexpression of CDC25C was associated with a later FIGO stage." (PMID 35574406, 2022). "In vulvar squamous cell carcinoma, overexpression of CDC25B, CDC25C, and phosphor-CDC25C is linked to malignant features and aggressive cancer phenotypes." (PMID 33925358, 2021). "The aims of our study were to determine expression statuses of CDC25A, CDC25B and CDC25C in a large series of vulvar squamous cell carcinomas to shed light on their roles in the pathogenesis of this cancer type and to clarify their potential prognostic values." (PMID 20500813, 2010).
bladder tumor (2 papers, 2013 to 2016). "Given that CDC25C gene expression increases with the degree of dedifferentiation, these immunohistochemical findings suggest that high tumoral expression of CDC25C protein signifies an increased extent of undifferentiated bladder tumor cells rather than exclusively triple-positive basal cells." (PMID 27775025, 2016).
chronic myeloid leukemia (2 papers, 2021 to 2025). "Moreover, an ethanol extract of a traditional Chinese medicine, Eupolyphaga sinensis Walker induced G2/M arrest of a chronic myeloid leukemia cell line K562 accompanying through downregulation of cyclin D1, cyclin E1 and cdc25C." (PMID 34513690, 2021).
colon adenocarcinoma (2 papers, 2023 to 2025). "Compared with tumor adjacent tissues, EEF1A2, PBK and TIMP1 showed significant upregulation in colon adenocarcinoma, while ATP2A3, CDC25C, MMP3 and NAT1 showed significant downregulation." (PMID 37626132, 2023).
COVID-19 (2 papers, 2021 to 2023). A disease caused by infection with severe acute respiratory syndrome coronavirus 2. "In our study, the levels of CDC6, CDC25C, and KIF15 were down-regulated in both the COVID-19 and SLE datasets, suggesting a better prognosis with these genes." (PMID 37426642, 2023). "The area under the curve (AUC) values for 6 shared hub genes (CDC6, PLCG1, KIF15, LCK, CDC25C, and RASGRP1) in the SLE dataset to discriminate between patients and healthy controls were greater than 0.61, while those for the COVID-19 dataset were greater than 0.91." (PMID 37426642, 2023).
diffuse large B-cell lymphoma (2 papers, 2018 to 2025). "CDC20 and CDC25C are highly expressed in diffuse large B cell lymphoma, suggesting that these genes may also influence B cell growth and development." (PMID 40565588, 2025). "Phosphorylation of cdc25c and H2AX was constitutively detected in diffuse large B-cell lymphoma (DLBCL)." (PMID 29861856, 2018).
multiple myeloma (2 papers, 2019 to 2024). "The organotellurate immunomodulator AS101 induces G2/M arrest in myeloma cells and downregulates Cdc25C, Plk-1 (a serine/threonine kinase), and Ilk-1 (essential for regulating the activity of Akt) in mouse 5T33 myeloma cells." (PMID 31772702, 2019).
non-small cell lung carcinoma (2 papers, 2022 to 2025). A group of at least three distinct histological types of lung cancer, including non-small cell squamous cell carcinoma, adenocarcinoma, and large cell carcinoma. "There was a trend towards shorter PFS for non-small cell lung cancer patients with higher CDC25C expression (high vs. low: 1.55 months vs. 5.45 months, P = 0.0693)." (PMID 35574406, 2022).
osteosarcoma (2 papers, 2019). A usually aggressive malignant bone-forming mesenchymal neoplasm, predominantly affecting adolescents and young adults. "The data showed that the protein level of phospho-cdc2, cdc2, and Cdc25C were decreased in treated both cell lines, but Cyclin B1 protein levels had no apparent change in HOS cells and was decreased in MG-63 cells, indicating Licochalcone A induces G2/M phase arrest of osteosarcoma cell lines." (PMID 31269698, 2019).
prostate adenocarcinoma (2 papers, 2016 to 2025). "In particular, transcript levels of Cdc25C negatively correlated with CLU expression across 460 prostate adenocarcinoma human tissue samples (P < 0.001; r = −0.23)." (PMID 27198502, 2016).
thyroid cancer (2 papers, 2015 to 2025). "Our data showed that SFN-treated thyroid cancer cells were arrested in G2/M phase, which was accompanied by a decline in the levels of Cdk1, Cdk2, Cyclin B1 and Cdc25C and an increase in the levels of Chk1 and p21." (PMID 26312762, 2015).
acute lymphoblastic leukemia (1 paper, 2024). Leukemia with an acute onset, characterized by the presence of lymphoblasts in the bone marrow and the peripheral blood. "Our studies revealed that ISAE induces G2/M arrest in the T cell acute lymphoblastic leukemia cell line—Jurkat cells, and stimulates the ATR/CHK1/Wee1/CDC25C signaling pathway." (PMID 38195460, 2024).
Ad- (1 paper, 2016). "In this study, we observed that Ad-RAD50 infection decreased the phosphorylation of cdc25c and cdk1." (PMID 26951044, 2016).
bladder urothelial carcinoma (1 paper, 2021). "We also explore the predictive value of these six cell cycle related genes and found that CCNB1, CDC20 and CDC25C could also predict the overall survival rate of bladder urothelial carcinoma patients." (PMID 33980246, 2021).
breast tumors (1 paper, 2016). "Furthermore, SL4 suppressed the growth of established breast tumors in nude mice through upregulation of p21 and downregulation of cdc25C, and displayed a good safety profile." (PMID 27819344, 2016).
colorectal adenocarcinoma (1 paper, 2020). The most common type of colorectal carcinoma. "In LoVo human colorectal adenocarcinoma cells, BBR dose- and time-dependent treatment downregulated cell cycle protein, such as cyclin B1, cdc25c, and cdc2, leading to cell cycle arrest in G2/M phase and suppression of colorectal adenocarcinoma cell growth." (PMID 32855766, 2020).
cyst (1 paper, 2019). A sac-like closed membranous structure that may be empty or contain fluid or amorphous material. "Growth-promoting cell cycle checkpoint proteins (phosphorylated retinoblastoma, cdk1, cdc25C) were decreased and the inhibitory cell cycle protein p27 was increased by the combination of cyst(e)inase and auranofin." (PMID 31231686, 2019).
esophageal cancer (1 paper, 2022). A primary or metastatic malignant neoplasm involving the esophagus. "Although there is sufficient evidence that CDC25C promotes tumor progression, high CDC25C expression enhances the sensitivity of esophageal cancer to radiotherapy." (PMID 35574406, 2022).